CDKL5 (cyclin dependent kinase like 5)
Diseases named in the same sentence as CDKL5 in open-access papers (continued):
Sharing a sentence is not in itself a finding about the gene and the disease.
Rett syndrome (continued). "Reports indicate that NTNG1 is a causative gene of the atypical Rett syndrome, since CDKL5 has historically been considered causative gene of the atypical Rett syndrome, suggesting that NGL-1 is one of the physiological substrates of CDKL5." (PMID 32587608, 2020). "However, those with Rett syndrome were more likely to develop scoliosis than those with the CDKL5 disorder (log rank test p = 0.002)." (PMID 27080038, 2016). "However, the incidence of gastrostomy insertion was higher in the CDKL5 disorder affected females (3.2 insertions per 100 person-years) than in Rett syndrome (1.9 insertions per 100 person-years)." (PMID 27080038, 2016). "During the last years, the cyclin-dependent kinase-like 5 gene (CDKL5; OMIM 300203), located on the X-chromosome, has been associated with severe encephalopathy associated with X-linked infantile spasms and some Rett syndrome (RTT)-like features." (PMID 26849555, 2016). "Eventually, autonomic features such as breathing irregularities, cold extremities, and gastrointestinal disturbances might occasionally be found in CDKL5 patients, whereas they are consistently found in Rett syndrome." (PMID 22779007, 2012). "A closely linked upstream gene on the X chromosome named cyclin-dependent kinase-like 5 (CDKL5) may also be involved in Rett syndrome." (PMID 22937247, 2011). "To determine if elevated DNA damage is potentially a trigger of Rett syndrome phenotypes irrespective of the nature of the mutation, we also assessed isogenic neurons from hiPSCs derived from patients with Rett syndrome caused by mutations in CDKL5." (PMID 41005313, 2025). "In the following review we compare the overlapping and contrasting features in Rett syndrome (RTT) and CDKL5 disorder (CDD) in clinic, as well as their respective rodent models." (PMID 31618813, 2019).
Rett syndrome (continued). "Unlike Rett syndrome, very little is known about the full range of comorbidities occurring in the CDKL5 disorder with available literature mainly limited to small case series or studies." (PMID 27080038, 2016). "Similarly to Rett syndrome, the mechanism by which absence of Cdkl5 induces microglia overactivation appeared to be non-cell autonomous." (PMID 34238328, 2021).
Intellectual disability (44 papers, 2015 to 2026). "CDD is a severe neurodevelopmental condition, characterized by early-onset seizures, intellectual disability, and motor impairments due to pathogenic variants in the CDKL5 gene." (PMID 41230376, 2025). "Mutations in the X-linked gene cyclin-dependent kinase-like 5 (CDKL5) cause a severe neurological disorder characterised by early-onset epileptic seizures, autism and intellectual disability (ID)." (PMID 38877552, 2024). "Disruption to the subcellular regulation of HDAC4 has also been implicated in CDKL5 disorder, in which mutations in cyclin dependent kinase-like 5 (Cdkl5) cause severe intellectual disability and motor impairment." (PMID 38167120, 2024). "CDKL5 (cyclin-dependent kinase-like 5) deficiency disorder is a rare disease associated with intellectual disability and impaired sociability." (PMID 39056071, 2024). "The largest inversion was a de novo 36.4-Mb variant (chrX:18,472,998–54,910,892, GRCh38) that disrupts CDKL5 in an individual with intellectual disability and seizures, consistent with a diagnosis of developmental and epileptic encephalopathy 2 (MIM: 300672)." (PMID 38776926, 2024). "Mutations in the CDKL5 gene lead to the CDKL5-deficiency disorder, a rare neurological condition characterized by the onset of seizures in the first weeks of life and severe intellectual disability." (PMID 37834063, 2023). "CDKL5 (cyclin-dependent kinase-like 5): CDKL5 deficiency disorder is a rare epileptic encephalopathy characterized by early-onset seizures, severe developmental delay, and intellectual disability." (PMID 37927689, 2023). "Cyclin dependent kinase like 5 (CDKL5) KO mice, a mouse model of CDKL5 deficiency disorder, exhibit seizures in early life, as well as intellectual disability later during development." (PMID 35447949, 2022). "Cyclin dependent kinase-like 5 (CDLK5) disorder is a neurodevelopmental disorder associated with intellectual disability, and CDLK5 mutant mice display deficits in neuronal survival and maturation as well as impaired hippocampal-dependent memory." (PMID 33859551, 2021). "Although CDD is rare, it was recently discovered that CDKL5 is one of the most commonly mutated genes in childhood epilepsy, and CDKL5 mutations have also been associated with milder syndromes typified by intellectual disability and behavioural defects." (PMID 34605059, 2021). "Autistic-like (ASD-like) features, including disinterest in the surrounding environment, intellectual disability, and motor dysfunction are prominent features of CDKL5 deficiency and have been commonly described in Cdkl5 KO mouse models." (PMID 34094641, 2021). "The clinical features commonly associated with CDKL5 mutations include early-onset seizures, cortical visual impairment, intellectual disability, and gross motor impairment." (PMID 34094641, 2021). "Mutations in the CDKL5 gene lead to an incurable rare neurological condition characterized by the onset of seizures in the first weeks of life and severe intellectual disability." (PMID 31450582, 2019). "CDKL5 disorder is a rare, debilitating form of early infantile epileptic encephalopathy and severe intellectual disability caused by a range of de novo mutations in the CDKL5 gene." (PMID 27315173, 2016). "Severe intellectual disability is a central feature of human CDKL5 deficiency." (PMID 29977282, 2018). "CDKL5-deficiency disorder or CDD, which results in intellectual disability, speech, and motor deficits, and seizures that can start as early as 6 weeks after birth, is caused by de novo mutations in the CDKL5 gene." (PMID 42167577, 2026). "Mutations in CDKL5 are associated with a rare neurodevelopmental disease called CDKL5 deficiency disorder (CDD), which is characterized by early‐onset seizures and intellectual disabilities." (PMID 40847610, 2026).
Intellectual disability (continued). "Variants in the protein kinase CDKL5 cause CDKL5 Deficiency Disorder (CDD), a severe neurodevelopmental condition characterized by seizures, developmental delay, and intellectual disability." (PMID 41385589, 2025). "CDKL5 deficiency disorder (CDD) causes seizures, developmental delay, and severe intellectual disability in affected individuals." (PMID 41385589, 2025). "These include sequencing of the CDKL5 gene, the use of a panel of known genes for epilepsy disorders or intellectual disability, whole exome or genome sequencing, or, in rare cases, chromosomal microarray." (PMID 38450883, 2024). "Mutations in the X-linked CDKL5 gene underlie a severe epileptic encephalopathy, CDKL5 deficiency disorder (CDD), characterized by gross motor impairment, autistic features and intellectual disability." (PMID 39592934, 2024). "The research on “beyond ion channel diseases” ranges from “phenotypes” to “infantile spasms,” “intellectual disability,” “DNA copy number variations,” “developmental disabilities,” and “CDKL5” which seems continually to be the focus in the future." (PMID 31393404, 2019). "Mutations in cyclin-dependent kinase-like 5 (CDKL5) cause a severe neurodevelopmental disorder characterized by early-onset seizures, intellectual disability, and autistic features." (PMID 31201320, 2019). "Mouse models of CDKL5 deficiency disorder (CDD) recapitulate multiple clinical symptoms of CDD, such as intellectual disability and autism." (PMID 31201320, 2019). "Heterozygous rare variants in X-linked CDKL5 in females cause EIEE, severe intellectual disability and Rett-like features (MIM: 300672)." (PMID 30526634, 2018). "The cyclin-dependent kinase-like 5 (CDKL5) gene has been associated with rare neurodevelopmental disorders characterized by the early onset of seizures and intellectual disability." (PMID 28740074, 2017). "In accordance with its involvement in intellectual disability, CDKL5 is highly abundant in brain where it is significantly induced in early post-natal stages suggesting a role in brain maturation." (PMID 26849555, 2016). "Regarding X-linked mutations, we identified alterations in two genes (MAOA and CDKL5) previously associated with ASD and intellectual disability." (PMID 25969726, 2015). "Moreover, previous research has demonstrated that IEM-1460 can rescue the phenotype of a mouse model of CDKL5 deficiency disorder (CDD), characterized by intellectual disability, autistic-like behaviors, and seizure behavior." (PMID 38227384, 2024). "For instance, an increased dosage of the CDKL5 gene has been linked to a variety of symptoms, such as microcephaly, intellectual disability, limited hand skills, hypotonia, lack of eye contact, absence of speech and walking, seizures, and ataxia." (PMID 39062680, 2024). "Recently, we assessed the presence of pupillary abnormalities in a mouse model of cyclin-dependent kinase-like 5 (Cdkl5) deficiency disorder (CDD), a severe neurodevelopmental disorder characterized by early-onset seizures, intellectual disability, motor and cortical visual impairment." (PMID 37063384, 2023). "Dozens of mutations of the CDKL5 gene are causative of CDKL5 Deficiency Disorder (CDD; OMIM 300203; 300672), a severe condition that is manifested with intellectual disability, autistic behavior, motor and visual impairments, infantile-onset refractory epilepsy, and many other symptoms." (PMID 36242022, 2022).
Intellectual disability (continued). "Cyclin-dependent kinase-like 5 (CDKL5) deficiency disorder (CDD) is a rare encephalopathy characterized by early-onset intractable epileptic seizures, severe intellectual disability, gross motor impairment, stereotypies, visual impairments and autistic-like features." (PMID 31114483, 2019). "The marked intellectual disability and various comorbidities among children with the CDKL5 disorder may lessen the influence of seizures alone on the primary caregiver’s health." (PMID 28103894, 2017). "If we were to subtract the cost of every single gene test from C1's cost analysis (cost for batten screen, CDKL5, SCN1A gene sequencing, Rett gene sequencing, ATP7A for Menkes disease, and X-linked mental retardation-sequencing of a panel of 7 genes), the excess cost would have still been $13,055." (PMID 27243033, 2016). "Mutations in the X-linked cyclin-dependent kinase-like 5 gene (CDKL5) are associated with CDKL5 deficiency disorder (CDD [MIM300203]), a neurodevelopmental disease characterized by early infantile epileptic encephalopathy, autism spectrum disorders, and intellectual disability." (PMID 40042769, 2025). "Cluster 2 had a strong link with “infantile spasms” and “intellectual disability” resulting from non-ion channel abnormalities such as “CDKL5,” “gene defect,” and “copy number variations”." (PMID 31393404, 2019). "These phenotypes have been described in CDKL5 patients and may mimic the absence of hand skills, the intellectual disability, hyperactivity, poor response to social interactions, and breathing problems that have been described." (PMID 29977282, 2018).
Epileptic encephalopathy (39 papers, 2009 to 2026). A condition in which epileptiform abnormalities are believed to contribute to the progressive disturbance in cerebral function. "Cyclin-dependent kinase-like 5 (CDKL5) deficiency disorder (CDD) is a severe developmental and epileptic encephalopathy characterized by early onset drug-resistant seizures and later cognitive and social impairments." (PMID 41709000, 2026). "In humans, pathogenic variants of CDKL5 cause severe developmental and epileptic encephalopathy, accompanied by multisystemic comorbidities as a consequence of CDKL5 deficiency." (PMID 40649845, 2025). "This work, in our opinion, provided fresh insight into the epileptic encephalopathies linked to CDKL5 and highlighted Cav2.3 as a possible target for it." (PMID 40217367, 2024). "CDD is a rare X-linked dominant genetic condition associated with severe and drug-resistant epileptic encephalopathies caused by the loss of function of the CDKL5 gene." (PMID 39000022, 2024). "CDKL5 is a brain-enriched serine/threonine kinase, associated with a profound developmental and epileptic encephalopathy called CDKL5 deficiency disorder (CDD)." (PMID 38326557, 2024). "Our results indicate that developmental and epileptic encephalopathies caused by CDKL5 and CACNA1E are related at the molecular level." (PMID 38081835, 2023). "Studies support the safety and efficacy of fenfluramine (FFA) as an antiseizure medication (ASM) in Dravet syndrome, Lennox‐Gastaut syndrome, or CDKL5 deficiency disorder, all pharmacoresistant developmental and epileptic encephalopathies." (PMID 35599347, 2022). "Variants in CDKL5 are typically associated with early onset epileptic encephalopathy with seizures usually starting between three and six months of age." (PMID 34469436, 2021). "CDKL5-related encephalopathy is an X-linked dominant disorder that is characterized by early infantile epileptic encephalopathy that is clinically distinct from RTT." (PMID 26236194, 2015). "Nine females and one male with CDKL5 gene mutations are found in 102 patients with early-onset epileptic encephalopathy and RTT." (PMID 24564546, 2014). "Mutations in the X-linked cyclin-dependent kinase-like 5 (CDKL5) gene cause early-onset epileptic encephalopathy." (PMID 24838000, 2014). "The cyclin-dependent kinase-like 5 (CDKL5) deficiency disorder (CDD) is a rare developmental and epileptic encephalopathy that is caused by mutations in the CDKL5 gene, which encodes a serine/threonine kinase that is essential for neuronal development, synapse formation, and axonal growth." (PMID 40290041, 2025). "73% of patients with CDKL5 mutations showed drug-resistant epileptic encephalopathy." (PMID 38540345, 2024). "Developmental and epileptic encephalopathies are severe neurological conditions in clinical practice, among which loss-of-function mutations in brain-enriched serine-threonine kinase cyclin dependent kinase like-5 (CDKL5) exists as one of the most common types." (PMID 40217367, 2024). "Due to the limited therapeutic possibilities, patients with CDKL5 deficiency disorder (CDD) may experience permanent symptoms of epileptic encephalopathy and significant developmental impairment." (PMID 32079229, 2020). "Variations in CDKL5 are associated with epileptic encephalopathy." (PMID 26236194, 2015). "Whether the impairment seen in the CDKL5 disorder is a direct result of the occurrence of infantile seizures, resulting in an epileptic encephalopathy, or whether it is a consequence of the underlying gene mutation, is yet to be determined and further research in this area is needed." (PMID 25657822, 2015). "Cyclin-dependent kinase-like 5 (CDKL5) deficiency disorder, which is a developmental and epileptic encephalopathy occurring in 1 in every 40,000 to 60,000 live births, was the subject of this computational investigation." (PMID 40943322, 2025).